TIMP3 (TIMP metallopeptidase inhibitor 3)
Diseases named in the same sentence as TIMP3 in open-access papers (continued):
Sharing a sentence is not in itself a finding about the gene and the disease.
keratoconus (6 papers, 2009 to 2024). A degenerative, structural disorder of the eye, characterized by a cone-shaped protrusion of the cornea. "Furthermore, alterations in the genes encoding tissue inhibitor of metalloproteinase 3 (TIMP-3) and cathepsin are also found in a cornea with keratoconus." (PMID 20170483, 2010). "LOX and TIMP3 play a pivotal role in extracellular matrix maturation and remodeling, respectively, two process that could influence the loss of corneal structural components, leading to corneal thinning typical of keratoconus." (PMID 21976959, 2011). "And some of their target genes, such as FN1, COL12A1, TIMP3 and FBLN5, were associated with ECM and also down-regulated in keratoconus." (PMID 35821117, 2022). "In this study, we report the mutational analysis results for VSX1, LOX, SPARC, TIMP3, and SOD1, performed in a large cohort of Italian subjects affected by sporadic and familial keratoconus." (PMID 21976959, 2011). "Because the expression of TIMP3 in keratoconus was decreased relative to the normal cornea, it was suggested that the decreased expression of this gene caused the imbalance between the destruction and reformation of interstitial substances." (PMID 19956410, 2009). "Statistical univariate analysis of TIMP-3 for its usefulness as a potential predictor of keratoconus showed itssensitivity of 54% and specificity of almost 90% which probably indicates its smaller importance in the etiopathogenesis of keratoconus compared to TIMP-1 and TIMP-2." (PMID 38398480, 2024). "High diagnostic sensitivity and specificity values of TIMP-1 and TIMP-2 and high diagnostic specificity values of TIMP-3 and TIMP-4 in relation to keratoconus were demonstrated, which confirms their strong role in the etiopathogenesis of this disease, especially when they all interact together." (PMID 38398480, 2024). "TIMP-1, TIMP-2, TIMP-3, and TIMP-4 values were analyzed for their usefulness as potential predictors of keratoconus." (PMID 38398480, 2024). "The aim of the study was to determine the concentration of the TIMPs TIMP-1, TIMP-2, TIMP-3, and TIMP-4 in the blood serum samples of patients with keratoconus compared to the control group." (PMID 38398480, 2024). "However, we assessed the expression of eight genes in more detail by employing RT-PCR and real-time PCR, which confirmed the overexpression of BMP4, CFL1, and MRVI1, and the underexpression of ACTA2, GRCC10, TIMP3, TIMP1, and SSTR1 in keratoconus." (PMID 19956410, 2009).
tendinopathy (6 papers, 2013 to 2023). "Evidence on TIMPs showed that TIMP-1 expression is briefly augmented (compensation) after acute tendon tear and reduced in tendinopathy, whereas TIMP-2, TIMP-3, and TIMP-4 are downregulated in both tendinopathy and tears." (PMID 36830637, 2023). "However, MMP1, MMP13, MMP10, ADAMTS5, TIMP3, versican, aggrecan, biglycan, decorin, fibronectin, fibrillin and COMP showed an opposite response with strain compared to tendinopathy." (PMID 23830915, 2013).
acute myeloid leukemia (5 papers, 2009 to 2022). Acute myeloid leukemia (AML) is a group of neoplasms arising from precursor cells committed to the myeloid cell-line differentiation. "Shedding of NKG2D ligands, including MICA, MICB and ULBP2, is inhibited by TIMP-3 in acute myeloid leukemia (AML) cells, and this process enhances their sensitivity to lytic activity of NK." (PMID 35207132, 2022).
esophageal adenocarcinoma (5 papers, 2006 to 2025). A malignant tumor with glandular differentiation arising predominantly from Barrett mucosa in the lower third of the esophagus. "TIMP3 methylation has also been implicated in the development and progression of esophageal adenocarcinoma, and reduced TIMP3 expression has been associated with increased tumor invasiveness and poor prognosis." (PMID 37369946, 2023). "TIMP3 acts as a tumor suppressor gene, and decrease of TIMP3 expression has been found in esophageal adenocarcinoma, gastric adenocarcinoma, and clear cell renal cell carcinoma." (PMID 31624299, 2019). "This is consistent with the observation of Darnton and colleagues, who immunodetected TIMP-3 in normal and metaplastic esophageal epithelium as well as in esophageal adenocarcinoma." (PMID 17032447, 2006).
Hepatic fibrosis (5 papers, 2017 to 2025). The presence of excessive fibrous connective tissue in the liver. "In addition, our MASH EVs were significantly enriched with several ligands that are crucial in mediating liver fibrosis, including PDGFB, LTBP1 and TIMP3." (PMID 40313415, 2025). "We further demonstrated that miR-6676-3p downregulated the mRNA expression of α-SMA, COLLAGEN I, TIMP1, TIMP3 and upregulated MMP2, MMP9, which are all profibrogenic genes in which TIMP1/3 antagonize MMP2/9 which decompose the collagen I during the progression of liver fibrosis." (PMID 34930304, 2021).
intracerebral hemorrhage (5 papers, 2018 to 2026). A cerebrovascular disorder characterized by bleeding into one or both cerebral hemispheres including the basal ganglia and the cerebral cortex. "Therefore, this study was designed to explore the causal role of TIMP-3 in the risk of ischaemic stroke (IS) and intracerebral haemorrhage (ICH), which are the two main causes of stress via this Mendelian Randomisation (MR) study." (PMID 35444693, 2022). "Previous histologic studies in occipital lobe showed an altered ratio of MMP9 and TIMP3 in leptomeningeal vessels of CAA cases with intracerebral hemorrhage." (PMID 39039355, 2024). "Some scholars have studied in traumatic brain injury (TBI) or intracerebral hemorrhage (ICH), TIMP-1, or TIMP-3 released by MSCs could stabilize BBB integrity." (PMID 29724240, 2018).
kidney damage (5 papers, 2013 to 2024). "ADAM17 and its inhibitor TIMP3 are involved in nephropathy, but their role in diabetic kidney disease (DKD) is unclear." (PMID 23401241, 2013). "In human kidney disease, TIMP3 is primarily upregulated in proximal renal tubules and vascular compartments to mitigate interstitial nephritis and fibrosis, potentially serving as a protective mechanism to minimize kidney damage." (PMID 38774282, 2024). "Based on these data, we postulate that during early stages of kidney damage, renal ACE2 and sheddase activity of ADAM17 increase in the event of high circulating Ang II, while expression of renal TIMP3 is reduced." (PMID 23646149, 2013).
liver cancer (5 papers, 2020 to 2024). An epithelial or non-epithelial malignant neoplasm that arises from the liver. "The upregulation of TIMP3 by DZNep is associated with attenuating proliferation of liver cancer cells and an increased population of apoptotic cells." (PMID 38542164, 2024). "miR-181b decreases TIMP3 expression and promotes the tumourigenic properties of liver cancer cells in vitro and in vivo." (PMID 38542164, 2024). "For example, TIMP3 was reported to mediate promoting effects of miR-181b on tumour progression in CDAA-induced liver cancer in which TIMP3 was down-regulated." (PMID 35867177, 2022). "TIMP3 functions as a tumor suppressor in a variety of cancers, and its expression in liver cancer is silenced." (PMID 32724322, 2020). "In clinical studies, decreased expression of TIMP-3 was correlated with a poor prognosis of patients with colorectal and liver cancer." (PMID 33126605, 2020). "3-Deazaneplanocin A (DZNep), an EZH2 inhibitor, increased TIMP3 mRNA levels in liver cancer cells." (PMID 38542164, 2024). "The TIMP3 mRNA level in liver cancer tissues is lower than in paired adjacent non-cancerous tissues." (PMID 38542164, 2024).
macular degeneration (5 papers, 2013 to 2023). Loss of vision in the central portion of the retina (macula), secondary to retinal degeneration. "Emerging evidence suggests that alterations in specific genes encoding ECM proteins (TIMP3, CTRP5, FBN2, and FBLN 1–6) are implicated in macular degeneration." (PMID 27007659, 2016). "Previous research has confirmed that EFEMP1 bind to TIMP-3 in macular degenerative diseases; they colocalize in vivo and form a complex in situ." (PMID 25987128, 2015). "However, the role of TIMP3 in AMD is somewhat controversial as some have proposed, due to the penetrance of TIMP3 in subpopulations of patients with macular degeneration, that this particular gene may represent a specific and distinct disease subset." (PMID 27239555, 2016).
pancreatic cancer (5 papers, 2019 to 2025). "miR‐21 targets phosphatase and tensin homologue (PTEN), programed cell death 4 (PDCD4), tropomyosin 1 (TMP1), and tissue inhibitor of metalloproteinases 3 (TIMP3) genes in pancreatic cancer resulting in increased proliferation, invasion and chemoresistance." (PMID 39855897, 2025).
psoriasis (5 papers, 2014 to 2025). An autoimmune condition characterized by red, well-delineated plaques with silvery scales that are usually on the extensor surfaces and scalp. "The specific association of miR-222/TIMP3 has the potential to have a function in the etiology and progression of psoriasis." (PMID 40540498, 2025). "Previous studies have demonstrated that expression of miR-21 is significantly increased in 29 of the 32 psoriasis cases, and that expression of miR-21 is correlated to the low expression of metalloproteinase 3 (TIMP-3)." (PMID 33975513, 2021). "Most recently, it has been reported that microRNA-21 (miR-21) targeted TIMP-3 and was functionally involved in the pathogenesis of psoriasis." (PMID 25384035, 2014). "It was demonstrated that mice lacking Jun-B/c-Jun in the epidermis showed a down-regulation of TIMP-3, resulting in the generation of a psoriasis-like phenotype through massive TNF-α shedding by TACE activation." (PMID 25384035, 2014). "Notably, increased miR-221 and miR-222 also target TIMP-3 in psoriatic skin lesions, thus underscoring the potential importance of TIMP-3 and matrix metalloproteases in the immunopathogenesis of psoriasis." (PMID 33718413, 2021). "Likewise, TIMP-3 expression in the skin of K5.Stat3C mice was attenuated as the psoriasis-like lesions developed by TPA application." (PMID 25384035, 2014).
renal cell carcinoma (5 papers, 2015 to 2023). "TIMP3 acts as a tumour suppressor, and the loss of TIMP3 has been found in several human cancers, including renal cell carcinoma, and has been proved to promote tumour metastasis." (PMID 33560588, 2022). "Here, our data showed the loss of TIMP3 caused by circCSNK1G3/miR‐181b in renal cell carcinoma promoted the cell proliferation, colonization, migration and invasion." (PMID 33560588, 2022). "Furthermore, in high-grade renal cell carcinoma tumors, TIMP3 mRNA levels were significantly lower." (PMID 37006234, 2023).
thyroid (5 papers, 2012 to 2021). "This miRNA, together with miR-221, targets p27kip1, p57, PTEN, TIMP3, and c-KIT, and it may play an essential role in thyroid carcinogenesis." (PMID 31636734, 2019).
type 2 diabetes (5 papers, 2016 to 2023). "On the other hand, TIMP3 deficiency in insulin receptor-haploinsufficient mice promotes type 2 diabetes and vascular inflammation." (PMID 27126782, 2016). "Authors showed that at level of human carotid atherosclerotic plaques, TIMP3 was significantly impaired in patients with type 2 diabetes, leading to A Disintegrin And Metalloproteinase (ADAM17) and MMP9 overactivity." (PMID 38304233, 2023). "This study suggested that in patients with type 2 diabetes, the deregulation of ADAM17 and MMP9 activities in atherosclerotic plaques is associated with an impaired expression of TIMP3 via SIRT1." (PMID 38304233, 2023).
aortic aneurysm (4 papers, 2017 to 2025). A ruptured aneurysm located in the wall of the proximal portion of the descending aorta proceeding from the arch of the aorta. "TIMP-3 deficiency promotes atherosclerosis and aortic aneurysm formation and reduces the beneficial effects of miR-181b inhibition." (PMID 27756793, 2017). "Taken together, our results imply that miR-181b is a critical regulator of macrophage TIMP-3 expression during the progression of atherosclerosis and aortic aneurysms." (PMID 27756793, 2017). "Inhibition of miR-181b protects against atherosclerosis and aortic aneurysm through increasing expression levels of macrophage TIMP-3 and vascular smooth muscle cell elastin." (PMID 27756793, 2017). "In this study, we show that genetic deletion of TIMP-3 results in more advanced atherosclerotic plaques and aortic aneurysms." (PMID 27756793, 2017). "In addition, given the protective role of TIMP3 in aortic aneurysm, and its dose-dependent function in angiogenesis, many potential therapeutic functions of TIMP3 remain to be explored." (PMID 32612540, 2020). "TIMP-3 plays a key role in another cardiovascular condition characterized by an excess of ECM turnover, the aortic aneurysm." (PMID 35207132, 2022).
cardiomyopathy (4 papers, 2010 to 2024). A disease of the heart muscle or myocardium proper. "A null mutation may also be of concern as TIMP3 knock out mice have present with pulmonary alveolar enlargement, enhanced susceptibility to cardiomyopathy, and hepatic injury, highlighting the need to silence selectively only the mutated allele." (PMID 36421778, 2022). "The mitigation of cardiomyopathy by tempol is reinforced by attenuation of MMP-9, TIMP-3 and induction of TIMP-4." (PMID 20828387, 2010).
colitis (4 papers, 2020 to 2022). Inflammation of the colon. "MCJ absence during colitis results in the upregulation of the Tace inhibitor Timp3, which inhibits TACE activity probably affecting Tnf and Tnfr1 shedding from the cell membrane." (PMID 31953445, 2020). "Furthermore, TIMP-3-KO mice developed more severe colitis after TNBS administration than TIMP-3–transgenic mice." (PMID 33802197, 2021). "They found that Timp3-null mice developed severe colitis after administration of TNBS, while mice overexpressing TIMP-3 were resistant to the disease." (PMID 35207132, 2022).
colorectal tumor (4 papers, 1997 to 2025). "Moreover, we found an association of SLC5A8 and TIMP3 DNA methylation with BRAFV600E in our colorectal tumor samples, as had been previously reported in papillary thyroid carcinomas." (PMID 20027224, 2009). "In our investigation, we observed a positive correlation between TIMP3 expression and macrophage infiltration in patients with colorectal tumors, as evident from the data analysis using the TIMER and GEPIA programs." (PMID 41009435, 2025).
COVID-19 (4 papers, 2020 to 2022). A disease caused by infection with severe acute respiratory syndrome coronavirus 2. "The enzyme activity of ADAM17 is inhibited and regulated by TIMP3, but SARS-CoV-2 reduces TIMP3 mRNA expression in alveolar epithelial cells, that likely promotes greater ADAM17 activity in COVID-19 patients." (PMID 32664949, 2020). "When not inhibited by TIMP-3, due to low SIRT1 activity-mediated TIMP-3 reduction, ADAM17 causes the release of TNF-α and IL6 and contributes to inflammation and possibly to the development of an uncontrolled hyperinflammatory response in COVID-19." (PMID 35457123, 2022).
disc degeneration (4 papers, 2012 to 2025). "Tissue inhibitor of metalloproteinase 3 (TIMP-3), inhibits aggrecanase and therefore, an increase in the level of TIMP-3 slows disc degeneration." (PMID 24250727, 2013). "Partially supporting these human data, the current animal model results indicate a differential expression pattern of TIMP-3 in disc degeneration." (PMID 22394620, 2012). "Although these catabolic factors were counteracted by even higher and increasing expression levels of their natural endogeneous inhibitors such as TIMP-1, TIMP-2, TIMP-3 and TIMP-4, we recoded declining levels of aggrecan and collagen II with increased severity of disc degeneration." (PMID 39286594, 2024). "Moreover, despite the concurrent increase of TIMP1, a major MMP inhibitor, alongside MMPs during disc degeneration, TIMP3 exhibits a distinct behaviour, not following the trajectory of cell immunopositivity for ADAMTS during degeneration." (PMID 39890859, 2025).
head and neck squamous cell carcinoma (4 papers, 2018 to 2025). A squamous cell carcinoma that arises from any of the following anatomic sites: lip and oral cavity, nasal cavity, paranasal sinuses, pharynx, larynx, and salivary glands. "TIMP-3 hypermethylation was found in HPV-positive oropharyngeal squamous cell carcinoma as well as head and neck squamous cell carcinoma incidence." (PMID 29467412, 2018).
Hepatic steatosis (4 papers, 2011 to 2024). Steatosis is a term used to denote lipid accumulation within hepatocytes. "Studies have reported that the deficiency of TIMP3 induces hepatic steatosis and adipose tissue inflammation in mice." (PMID 38558505, 2024). "The association of TIMP3 with liver steatosis is explained, but only in part by gut microbiome dysbiosis, suggesting that TIMP3/ADAM17 dyad exerts both broad and local effects to modulate immune and metabolic pathways." (PMID 28751722, 2017). "This phenotype is also partly due to enhanced adipose tissue hypertrophy, inflammation, and hepatic steatosis in Insr+/−/TIMP3+/− mice compared to WT and single heterozygote Insr+/− or TIMP3+/− mice." (PMID 37445827, 2023). "In contrast to TIMP3, TIMP4 deficiency is protective against HFD-induced hepatic steatosis as demonstrated by the robust decrease in liver expression of the rate-limiting enzyme stearyl CoA desaturase 1 (Scd1) in TIMP4−/− mice compared with WT under a HFD." (PMID 37445827, 2023).
ischemia (4 papers, 2011 to 2022). A hypoperfusion of the BLOOD through an organ or tissue caused by a PATHOLOGIC CONSTRICTION or obstruction of its BLOOD VESSELS, or an absence of BLOOD CIRCULATION. "Our results suggested that focal ischemia leads to proliferation of immature OLs in white matter and that TIMP-3 contributes to a caspase-3-dependent immature OL death via TNF-α-mediated neuroinflammation." (PMID 21871134, 2011). "Molecular analysis revealed an increase in TIMP1, TIMP2, and TIMP3 mRNA expression soon after ischemia onset in the whole area at risk, while no variations in the evaluated MMPs were observed." (PMID 32727469, 2020). "After ischemia, upregulated expression of tissue inhibitors TIMP1, TIMP2, TIMP3 and CTGF was observed in both the necrotic and salvaged myocardium." (PMID 32727469, 2020). "TIMP3 mRNA expression was only elevated in necrotic but not salvaged myocardium after severe ischemia." (PMID 32727469, 2020).
Myocardial fibrosis (4 papers, 2021 to 2023). "Loss of TIMP3 increased myocardial fibrosis and elevated the expression of MMP2 and MMP9 to a greater extent in iron-overloaded mice." (PMID 34722652, 2021). "Many ECM remodeling genes were upregulated with LAL (6 types of collagen; laminin, fibronectin, 2 types of LOXL, 3 types of MMP, TIMP3), suggesting myocardial fibrosis or fibroelastosis, which agreed with previous findings in this disease model." (PMID 37032398, 2023). "Deletion of TIMP3 also exacerbated myocardial fibrosis induced by angiotensin II." (PMID 34778374, 2021). "Thus, TIMP3 can be a powerful therapeutic candidate for strategies aimed at blocking myocardial fibrosis in the early stages of heart disease." (PMID 34141473, 2021). "On the other hand, the N-terminus of TIMP3 molecule with preserved MMP-inhibitory activity did not affect the collagen accumulation in a pig MI model, but the full-length TIMP3 reduced myocardial fibrosis." (PMID 34778374, 2021).
retinal degeneration (4 papers, 2019 to 2024). Degeneration of the retina. "In RPE, several proteins associated with retinal degeneration were downregulated (e.g., TIMP3, RDH5, PRELP)." (PMID 38605034, 2024). "Patients with SFD should also be educated to avoid smoking and follow a diet rich in fruit and vegetables, as these 2 lifestyle habits can slow down the retinal degeneration induced by TIMP-3 mutations." (PMID 36197222, 2022).